NTRK1 (neurotrophic receptor tyrosine kinase 1)
Diseases named in the same sentence as NTRK1 in open-access papers (continued):
Sharing a sentence is not in itself a finding about the gene and the disease.
craniopharyngioma (1 paper, 2022). A benign, partly cystic, epithelial tumor of the sellar region, presumably derived from Rathke pouch epithelium. "We collected 61 craniopharyngioma (CP) specimens to investigate the expression of TrkA, β-catenin, BRAF gene mutation, and NTRK1 fusion in CP." (PMID 35707464, 2022).
cutaneous melanoma (1 paper, 2021). A primary melanoma arising from atypical melanocytes in the skin. "Further, through the GEPIA database, in cutaneous melanoma, we examined the association between the ERBBs and 31 genes were close to each other and frequently altered and observed that all the genes except KIT, ALK, NTRK1, FGFR4, and MET were affected by the changes of some ERBB family members." (PMID 33732282, 2021).
endometrioid tumor (1 paper, 2012). A benign, borderline, or malignant epithelial tumor of the female reproductive system characterized by the presence of glands and/or cysts lined by neoplastic cells that resemble endometrial cells. "TPM3 was specifically amplified in endometrioid tumors and the gene has been shown to constitute a fusion gene with NTRK1 which belongs to the group of TRK oncogenes reported for papillary thyroid carcinoma." (PMID 23078675, 2012). "Interestingly, NTRK1 is also significantly amplified only in endometrioid tumors and further investigation is required to ascertain if this is due to gene fusion." (PMID 23078675, 2012).
Erdheim-Chester disease (1 paper, 2025). "Therefore, a retrospective analysis of 34 additional non-Langerhans cell histiocytoses (16 JXG, 3 adult xanthogranuloma and 1 benign cephalic histiocytosis, both clinical subtypes of JXG, as well as 13 Rosai-Dorfman and 1 Erdheim-Chester disease) for NTRK1, 2 and 3 aberrations was performed." (PMID 40235191, 2025).
histiocytic neoplasm (1 paper, 2025). Histiocytic tumors are a heterogeneous group of tumors and tumorlike masses commonly associated with histologically identical extracranial lesions. "Moreover, kinase fusions (e.g., involving BRAF, ALK, and NTRK1) have emerged as novel therapeutic targets in histiocytic neoplasms." (PMID 41562669, 2025).
insomnia (1 paper, 2022). A sleep disorder characterized by difficulty in falling asleep and/or remaining asleep. "These high-degree protein targets may be the key targets such as neurotrophic receptor tyrosine kinase 1, nuclear receptor subfamily 3 group C member 1, cyclin D1, erb-B2 receptor tyrosine kinase 2, and account for the essential therapeutic effects of CWT on insomnia." (PMID 36110515, 2022).
mood disorder (1 paper, 2020). A cognitive disorder a disturbance in which the person's mood is hypothesized to be the main underlying feature. "In light of these data supporting cholinergic hypersensitivity, the identification of a likely functional variant in the NTRK1 gene suggested the hypothesis that defects in TrkA lead to a defective cholinergic system, which in turn predisposes to mood disorders." (PMID 33235206, 2020).
myopericytoma (1 paper, 2025). A usually slow growing, subcutaneous nodular neoplasm arising from myopericytes. "Even though NTRK1 was negative, the lesion can still be clearly considered a malignant myopericytoma based on its morphology." (PMID 40522461, 2025).
nasopharyngeal carcinoma (1 paper, 2024). A carcinoma arising from the nasopharyngeal epithelium. "In nasopharyngeal cancer, Circlpo7 interacts with cytoplasmic YB1, promoting the phosphorylation of YB1 at S102, further promoting YB1’s nuclear translocation, and activating FGFR1, TNC, and NTRK1 transcription, thereby promoting nasopharyngeal cancer metastasis and resistance to cisplatin." (PMID 39497723, 2024).
neurofibroma (1 paper, 2019). An intraneural or extraneural neoplasm arising from nerve tissues and neural sheaths. "Interestingly, even though high NTRK1 expression is strongly associated with a favorable prognosis, NB and PCC/PGL have dramatically higher NTRK1 expression than neurofibroma, adrenal gland, or neural tube." (PMID 31681584, 2019).
oesophageal cancer (1 paper, 2022). "In the oesophageal cancer dataset, one case was found to have an NTRK1 fusion, for which entrectinib and larotrectinib are now approved in a solid tumour-agnostic manner." (PMID 35849877, 2022).
ovarian tumor (1 paper, 2020). "Local sequencing analysis of a biopsy from the primary ovarian tumor collected 2.5 months prior to the study start, approximately 3 weeks before cessation of letrozole therapy, revealed the presence of RET and TrkA (NTRK1) protocol-defined mutations." (PMID 32292573, 2020).
Pan (1 paper, 2023). "The relative proportion of NTRK1, NTRK2 and NTRK3 fusions varied across Pan Cancer cohorts but NTRK3 fusions were generally the most frequent." (PMID 36914665, 2023).
rectal cancer (1 paper, 2025). A primary or metastatic malignant neoplasm that affects the rectum. "NTRK alterations (NTRK1/2/3) were present in 0.9% and 0.5%, ROS1 alterations in 0.4% and 0.2%, RET alterations in 0.6% and 0.4%, and ALK alterations in 0.5% and 0.4% of samples in colon and rectal cancer, respectively." (PMID 39865537, 2025).
spinal cord tumour (1 paper, 2024). "A spinal cord tumour with the TPM3::NTRK1 fusion (patient #8, 2y/F) also exhibited a GBM-like pathology with MVP and necrosis." (PMID 39014476, 2024).
tauopathy (1 paper, 2025). Neurodegenerative disorders involving deposition of abnormal tau protein isoforms (tau proteins) in neurons and glial cells in the brain. "Since hyperphosphorylation of Tau leads to the formation of neurofibrillary tangles, a hallmark AD pathology, our in vitro findings suggest that targeting NTRK1 may help alleviate Tauopathy in AD neurons." (PMID 40502754, 2025).
thyroid nodule (1 paper, 2022). A small circumscribed mass in the THYROID GLAND that can be of neoplastic growth or non-neoplastic abnormality.
tumor (509 papers, 1997 to 2026). "We have developed and validated a novel TaqMan-based qRT-PCR assay to detect and quantify expression of the oncogenic NTRK1/TrkA splice variant TrkAIII in tumor tissues." (PMID 39941839, 2025). "Concurrently, two genes encoding neurotrophic factor receptors with tumor-suppressing effects—Ntrk1 and Erbb4—also exhibited markedly reduced expression levels." (PMID 41415031, 2025). "NTRK gene fusion-positive tumours are cancers with specific genetic abnormalities involving NTRK genes (NTRK1, NTRK2, NTRK3), which encode tropomyosin receptor kinase (TRK) proteins A, B, and C." (PMID 40141188, 2025). "P03 also has mutations in MTOR and ELF3, while P04 has mutations in FGFR1, and P05 has mutations in PIK3CA and NTRK1–genes involved in tumor growth and survival." (PMID 41012124, 2025). "One tumor had only a point mutation in NTRK1, while the remaining tumor showed 11 heterozygous deletions, including in ROS1, BCLAF1, and ARID1B, which were frequently altered in the entire cohort." (PMID 40227833, 2025). "A recent study demonstrated acquired SCP2:NTRK1 fusions associated with tumor progression on tamoxifen and letrozole treatment." (PMID 39038933, 2024). "This is one possible explanation for the short response in our patient who has co‐mutations identified in the initial tumour sample at diagnosis including NTRK1 over‐expression, TERT gain of function mutation and CDKN2A and CDKN2B loss." (PMID 39188081, 2024). "Tumor progression in both prostate carcinoma and breast cancer has been linked to an autocrine cycle involving NTRK1." (PMID 37446908, 2023). "Protein kinases play a critical role in PCa tumor proliferation, development, and metastasis, and several malignancies have been shown to cause changes in NTRK1 expression or mutations in this gene." (PMID 35627227, 2022). "The discovery of new molecular biomarkers in CRC and other cancers has begun to follow the approval of tumour-agnostic drugs, including NTRK1-3 translocations and high tumour mutational burdens (TMBs)." (PMID 36428637, 2022). "While MYCN promotes cell cycle progression and other features of aggressive tumor growth, NTRK1 induces differentiation and is associated with excellent patient outcome." (PMID 34771457, 2021). "The NTRK1 gene was mutated in 1 tumor (1.1%), showing one novel missense mutation outside the main domains of the protein." (PMID 31548566, 2019). "Multiple studies have linked NTRK1 overexpression to tumor progression and poor outcomes in solid cancers, and NTRK1 mutations confer acquired resistance to NTRK inhibitors." (PMID 29383146, 2017). "It is noteworthy that most of the suppressor mutations were found in the NTRK1 fusion-positive tumor with highly unstable microsatellites (Patient ID: LGP088T)." (PMID 26716414, 2016). "In addition, following tumour-agnostic drug approvals, new molecular biomarkers such as NTRK1-3 translocations and high tumour mutational burden (TMB) have emerged in CRC as well as in other malignancies." (PMID 35264786, 2022). "As represented in, there was an intermediate tumor mutational burden (TMB) in NTRK1." (PMID 35627227, 2022). "To date, three molecular targets (microsatellite instability-high (MSI-H) or mismatch repair deficient (MSI-H/dMMR), neurotrophic tropomyosin-related kinase (NTRK1/2/3) fusions or high tumor mutational burden (TMB-H)), have led to four site- or tumor-agnostic approvals by the FDA." (PMID 34198738, 2021). "Furthermore, based on our data, NTRK1 fusion-positive carcinomas were significantly associated with a higher frequency of tumor multifocality and distant metastases, and were more invasive than the carcinomas harboring a NTRK3 fusion." (PMID 33923728, 2021).
tumor (continued). "The absence of a known oncogenic driver mutation at Visit 1 may mean the NTRK1 fusion played a tumorigenic role and could have been an ideal drug target high on the tumor evolutionary tree." (PMID 32471990, 2020). "Moreover, sequence analyses have so far identified TrkAIII mRNA as the only NTRK1/TrkA splice variant in tumor samples with an in-frame tyrosine kinase domain and, therefore, oncogenic tyrosine kinase potential, which reinforces this hypothesis." (PMID 39941839, 2025). "Furthermore, one NTRK1-rearranged case with distant metastases (case 52) had synchronous sigma tumour with proficient (p)MMR and KRASG12V mutation, as was also shown to be the case for the peritoneal metastasis, whilst the NTRK1-rearranged tumour in colon ascendens was dMMR and RASwt." (PMID 35237889, 2022). "Notably, NTRK1 was present in 5% and a high tumor mutational burden in approximately 20%." (PMID 35326576, 2022). "NTRK fusions involve the TRK family (NTRK1–3) and are pan-tumor biomarkers effectively targeted by TRK-inhibitors such as larotrectinib and entrectinib." (PMID 40940901, 2025). "Accurate diagnosis of LMNA::NTRK1-rearranged neoplasms is clinically critical due to the availability of TRK inhibitors, which achieve response rates exceeding 75% in NTRK fusion-positive solid tumors." (PMID 41409361, 2025). "LMNA::NTRK1-rearranged neoplasms must be distinguished from several mimickers, particularly given their overlapping histomorphology and immunophenotype." (PMID 41409361, 2025). "This includes low prevalence biomarkers such as NTRK1, NTRK2, and NTRK3 (NTRK1/2/3) fusions as well as higher prevalence complex biomarkers such as tumor mutational burden-High (TMB-H)." (PMID 40748987, 2025). "In these cases, BRAF alterations function as tumor-agnostic predictive biomarkers, similar to NTRK1, NTRK2, and NTRK3 (NTRK1-3) gene fusions, supporting the rationale for broad molecular profiling and precision targeting strategies in rare GI tumors." (PMID 41153346, 2025). "Further collection of cases is needed to better understand the biological behavior and optimal management of LMNA::NTRK1-rearranged neoplasms." (PMID 41409361, 2025). "The FISH analysis demonstrated separated red and green fluorescence signals for the NTRK1 probe in tumor cells, indicating a rearrangement of the NTRK1 gene." (PMID 40936706, 2025). "We utilized an RNA hybrid capture-based NGS approach designed to detect fusions and splice variants in 55 genes including NTRK1, NTRK2, and NTRK3 fusions, resulting in a detection rate of 0.35% across a real-world, pan-tumor cohort." (PMID 40385986, 2025). "With evidence of a TPR::NTRK1 fusion-positive tumor, the patient began treatment with larotrectinib at a dose of 100 mg twice daily in June 2022." (PMID 38642578, 2024). "Despite these challenges, our study of twelve tumours harbouring NTRK1 or NTRK2 fusions revealed strong correlations and consistent positive results across various fusion partners." (PMID 39014476, 2024). "A tumour with the TPR::NTRK1 fusion that developed in the left temporo-occipital lobe of patient #4 (1 y/F) exhibited microscopic features compatible with DIG, CNS WHO grade 1." (PMID 39014476, 2024). "Pan-cancer predictive markers of tumor mutational burden (TMB) of 10 or more mutations per megabase, high microsatellite instability (MSI), or NTRK1/2/3 fusions were observed in 15.6%, 2.0%, and 0.1% of solid tumors, respectively." (PMID 37682776, 2024). "After analyzing the expression profiles of NTRK genes, we observed that the mRNA expression of NTRK1/2/3 was generally downregulated in tumor tissues compared to normal tissues across most cancers." (PMID 38357305, 2024).
tumor (continued). "This, therefore, points to hitherto unsuspected roles of cGMP in the intramolecular and downstream signaling of NTRK1 and the role of cGMP in NTRK1-dependent growth and neoplasia." (PMID 39273482, 2024). "The NTRK1/TRKA fusion has been linked to an improved prognosis and an increased likelihood of tumor regression." (PMID 38397049, 2024). "Collectively, the anti-tumor immunity in NTRK1/2/3 MT NSCLC was enhanced in some aspect compared with their WT counterparts, especially in patients with NTRK3 MT." (PMID 38031067, 2023). "While the analysis of ALK, ROS1, and RET rearrangements is generally limited to several tumor types, NTRK1, NTRK2, and NTRK3 are currently positioned as “agnostic” targets, calling, in theory, for systematic testing of the wide spectrum of tumors." (PMID 37762506, 2023). "Similar to other tumor types, TPM3::NTRK1, EML4::NTRK3 and ETV6::NTRK3 fusion variants represented the majority of NTRK1–3 translocations identified in this study." (PMID 37686416, 2023). "In this study, we showed that HGF, which can be produced by fibroblasts in the tumor microenvironment, induces entrectinib resistance by activating its receptor MET and downstream signaling pathways in NTRK1‐rearranged or ROS1‐rearranged tumor cells." (PMID 36416133, 2023). "From our tumor bank, we were able to obtain 39 samples with NTRK1 or NTRK3 fusions in which the presence of alteration was confirmed by variant-specific PCR or NGS." (PMID 37762506, 2023). "We found that HGF (produced by fibroblasts) induced entrectinib resistance in tumor cells with NTRK1 or ROS1 rearrangement and that HGF‐induced resistance was reversed by combination with HGF/MET inhibitors." (PMID 36416133, 2023). "This therefore points to hitherto unsuspected roles of cGMP in intramolecular and downstream signaling of NTRK1 and the role of cGMP in NTRK1-dependent growth and neoplasia." (PMID 38022692, 2023). "Ten cases showed NTRK1 split‐apart signals that were less than two signal diameters apart in approximately 5–15% of tumor cells analyzed." (PMID 37143440, 2023). "Underscoring its role in development and regulating cell growth, NTRK1 is also widely studied as tyrosine receptor kinase A (TrkA) which forms fusion proteins occurring in numerous tumor types." (PMID 38022692, 2023). "Since then, NTRK1–3 fusion genes have been identified in several tumor types and are present in < 1% of NSCLC cases." (PMID 37069698, 2023). "As the LMNA::NTRK1 fusion has been identified in different tumor types including carcinoma, we modeled the fusion in epithelial cells and evaluated the effect on cell proliferation/viability." (PMID 36801905, 2023). "This study shows the downregulation of NTRK1 in PCa cells, and thus its tumor-suppressive role is expected." (PMID 35627227, 2022). "Although NTRK1 was amplified in more than 70% of LUAD tumor samples, its mRNA expression was downregulated in LUAD tumor samples." (PMID 35936718, 2022). "In this study, we presented a case of MSI-H CRC patient with NTRK1 fusion who received anti-PD-1 treatment and experienced an increase in tumor size (SD) but pCR after resection." (PMID 36700211, 2022). "The TIMER database was used to evaluate the significant correlation of NTRK1 with tumor-infiltrating immune cells across TCGA-PRAD cohort." (PMID 35627227, 2022). "On the contrary, downregulating NTRK1 results in proliferation and angiogenesis and thus tumor growth and aggressiveness." (PMID 35627227, 2022).